DNMT1 (DNA methyltransferase 1)
Diseases named in the same sentence as DNMT1 in open-access papers (continued):
Sharing a sentence is not in itself a finding about the gene and the disease.
gastric cancer (continued). "A meta-analysis in gastric cancer suggested that rs16999593 in DNMT1 and rs1550117 in DNMT3A could contribute to GC risk and that rs1569686 in DNMT3B might be a protective factor." (PMID 35965507, 2022). "Although we confirmed in vitro that the SNHG3/miR-448/DNMT1 molecular axis mediates SEP9 methylation and thus affects the progression of gastric cancer, this study was limited in its ability to further verify this molecular mechanism in vivo." (PMID 35528235, 2022). "Silencing SNHG3 inhibited the expression of DNMT1 and SEPT9 methylation, and SEPT9 expression was upregulated and inhibited gastric cancer cell growth, metastasis, and spread." (PMID 35528235, 2022). "LncRNA HOXA11-AS promotes the invasion and proliferation of gastric cancer by regulating the chromatin modifiers LSD1 and DNMT1." (PMID 34134612, 2021). "DNMT1- and EZH2-mediated methylation contributes to the progression of gastric cancer and glioblastoma." (PMID 33743723, 2021). "In the nucleus, for example, lncRNA HOXA11-AS facilitates the proliferation and invasion of gastric cancer cells at epigenetic level through scaffolding the chromatin modification factors PRC2, LSD1, and DNMT1." (PMID 30987669, 2019). "The prediction identified three microRNAs (miR-21, miR-145 and miR-148a) and five gastric cancer-specific target genes (EGFR, KLF4, DNMT1 and AGO4) which also showed strong correlation with lncRNAs in regression analysis." (PMID 29719612, 2018). "In gastric cancer, HOXA11-AS not only acts as a scaffold for EZH2, LSD1 and DNMT1 but also functions as a molecular sponge for miR-1297 to antagonize its repressive effect on EZH2 translation." (PMID 29721215, 2018). "Although we found a differential expression of EGFR, FGFR2, KLF4, DNMT1 and AGO4 in gastric cancer samples, only FGFR2 overexpression was statistically significant (P = 0.0449)." (PMID 29719612, 2018). "In gastric cancer and glioma cells, knockdown of EZH2 not only impacted H3K27 trimethylation but also reduced DNMT1 presence on the miR-200b/a/429 promoter." (PMID 29221202, 2017). "Since LMP1 induces promoter hypermethylation via activation of DNA methyltransferase 1 and the polycomb group protein Bmi-1, LMP1 may contribute to global methylation and epigenetic silencing of multiple cancer genes during the initial stages of EBV-associated gastric cancer." (PMID 28454117, 2017). "Emerging studies found that the levels of DNMT1, DNMT3A, and DNMT3B mRNA are reportedly increased in various malignancies, including colorectal, liver, and gastric cancers." (PMID 19638978, 2009). "Indeed, methylation of GPX4 promoter catalyzed by DNMT1, DNMT3A and DNMT3B induces ferroptosis and viceversa the use of DNMT1 inhibitor induces ferroptosis in gastric cancer by indirect inactivation of the xCT system." (PMID 41339932, 2025). "In contrast, the expression of other DNMTs, such as DNMT3b and DNMT1 mRNA, was not affected by autophagy induction or inactivation in two independent gastric cancer cell lines (SGC7901 and BGC823)." (PMID 37477089, 2023). "It was reported that IL-1β could induce an increase in the DNMT activity via NF-κB pathway in gastric cancer cells and TGF-β1 could up-regulate the expression of DNMT1 and 3a though different mechanisms including activation of the PI3K/Akt pathway." (PMID 35265687, 2022). "In this study, we found that Linc00441 could recruit DNMT1 to the RB1 promoter and suppressed RB1 expression in gastric cancer cells." (PMID 30680063, 2018). "However, as reported for gastric cancer, TAMs are capable of silencing TSG gelsolin in cancer cells by increased DNMT1 expression and DNA methylation of gelsolin promoter via activation of CCL5/CCR5/STAT3 signaling." (PMID 30200265, 2018). "Study also demonstrated an interaction between DNMT1 and EZH2 in gastric cancer and glioma cells." (PMID 28360411, 2017).
gastric cancer (continued). "We also showed that DNMT1 could directly bind to SPRY4-IT1 promoter region and may contribute to the lost expression of SPRY4-IT1 in gastric cancer cells." (PMID 26238992, 2015). "We further analyzed in gastric cancer subtypes the expression of genes involved in epigenetic controls, such as EZH2 (Enhancer of zest homolog 2 involved in histone modifications), non-coding RNA (including long non-coding RNAs such as HOTAIR, H19) and DNMT1 (involved in DNA methylation)." (PMID 40868070, 2025). "We knocked out SNHG3 to inhibit the expression level of DNMT1 by regulating miR-448, which inhibits the methylation of SEPT9 mediated by DNMT1, upregulates the expression level of SEPT9, and prevents the invasion, metastasis, and spread of gastric cancer cells." (PMID 35528235, 2022). "We analyzed the expression level of gastric cancer-related genes EGFR, FGFR2, KLF4, DNMT1 and AGO4 identified through bioinformatics screening by relative quantification method and observed differential expression of EGFR, FGFR2, KLF4, DNMT1 and AGO4 in tumors." (PMID 29719612, 2018). "In addition, the expression of NKX6.3, Hace1, Nrf2, and DNMT1 was compared between non-neoplastic gastric mucosae and gastric cancers." (PMID 28584243, 2017). "Besides, methylations of HMLH1, p16 and CDH1 in gastric-cancer tissue samples at different progress periods do not correlate with the expression of DNMT1 directly." (PMID 21999220, 2011). "DNMT3A expression in gastric cancer (GC) has only been studied in protein levels and showed a significant overexpression of DNMT3A in tumours while DNMT1 and DNMT3B were only modestly over-expressed." (PMID 20128888, 2010). "While LMP2A can activate DNA methyltransferase 1 (DNMT1) through STAT3 phosphorylation, it may not be expressed in all epithelia cells of gastric cancers." (PMID 35053275, 2022).
hepatocellular carcinoma (107 papers, 2008 to 2026). A malignant tumor that arises from hepatocytes. "In support of this theory, it has been shown that mouse hepatoma Hepa-1c1c7 (Hepa-1) cells treated with chromate caused the cross-linking of DNMT1 with HDAC1, which resulted in reduced methylation activity; this may be attributed to Cr(III) formed upon the intracellular reduction of Cr(VI)." (PMID 39337613, 2024). "In HBV-associated hepatocellular carcinoma (HCC), DNMT expression is inversely correlated with levels of tumor suppressor microRNAs (miRNAs), including miR-152 targeting DNMT1 and miR-101 targeting DNMT3A." (PMID 29438328, 2018). "Compound 52 has been found to induce apoptosis in hepatocellular carcinoma cell lines by upregulating miR-370 through the AMPK/Sp1/DNA methyltransferase 1 (DNMT1) signaling pathway." (PMID 38535455, 2024). "Red raspberry extract enhanced PTEN activity through demethylating the PTEN gene promoter and inhibiting DNA methyltransferase-1 (DNMT1) expression, thus decreasing Akt activation in hepatocellular carcinoma cells." (PMID 38338464, 2024). "In hepatocellular cancer, miR-185-5p showed suppression of tumorigenesis through the blocking of the DNMT1/PTEN/Akt pathway." (PMID 38994952, 2024). "Taken together, these results showed that casticin has the ability to inhibit the stem cell-like phenotype of hepatocellular carcinoma by reversing the reciprocal negative regulation between DNMT1 and miR-148a-3p." (PMID 37304067, 2023). "In hepatocellular carcinoma, DNMT1 downregulation resulted in significant demethylation of the PROM1 promoter, resulting in its enhanced expression in a mechanism dependent on TGF-β stimulation." (PMID 37189618, 2023). "Similar reduction in p‐AKT expression along with DNMT1 was found in hepatoma cell line SK‐Hep‐1 with transient ZNF191 knockdown." (PMID 35092191, 2022). "Survival analyses with the univariate Cox regression model revealed their crucial roles in the patient outcomes, of these, DNMT3A, UHRF1, DNMT1, DNMT3B and TET1 the risk factors for hepatocellular carcinoma." (PMID 35771147, 2022). "Mechanistically, chlorogenic acid inhibited hepatocellular carcinoma growth by down-regulating DNA methyltransferase 1 (DNMT1) that assists with DNA methylation, the most prevalent epigenetic modification." (PMID 36431924, 2022). "A study demonstrated that DNMT1 was correlated with a poor prognosis of human hepatocellular carcinomas." (PMID 35838271, 2022). "To study the relationship of ZNF191 and DNMT1 in hepatoma cells, we analyzed the DNMT1 mRNA and protein expression in hepatoma cell Hep3B and PLC/PRF/5 with transient overexpressed ZNF191." (PMID 35092191, 2022). "In this study, we identified that transcription factor ZNF191 can positively regulate DNMT1 expression in hepatoma cells." (PMID 35092191, 2022). "Nonetheless, we identified DMS are enriched in the PI3K‐AKT pathway in both cell lines, and proved ZNF191/DNMT1/p‐AKT axis promote hepatoma cell growth." (PMID 35092191, 2022). "A study reported that DNMT1 is involved in the promotion of hepatocellular carcinoma, while this process has been proven to be inhibited by miR-185 by targeting the DNMT1/PTEN/AKT pathway." (PMID 35838271, 2022). "Insulin-like growth factor 1 (IGF1) dramatically increased DNMT1 expression in hepatocellular carcinomas (HCCs) via Akt/GSK-3β signaling pathway activation." (PMID 34162834, 2021). "Previously, we reported that 5-AZA-CdR and valproic acid (VPA) can inhibit DNMT1 in hepatocellular carcinoma (HCC)." (PMID 32337014, 2020). "Previously, we evaluated the effect of 5-Aza-CdR on DNA methyltransferase 1 (DNMT1) gene expression in hepatocellular carcinoma (HCC) which encouraged us to design the current study." (PMID 34466608, 2020). "In the same vein, silencing DNMT1 and DNMT3b in human hepatoma cells restores DR5 expression and TRAIL sensitivity." (PMID 31248188, 2019).
hepatocellular carcinoma (continued). "Activation of the p38 pathway induces hepatocellular carcinoma cell apoptosis through suppression of DNMT1 expression." (PMID 30363984, 2018). "Whereas, miR-152 reduces the levels of DNA methyltransferase 1 (DNMT1) in HBV induced Hepatocellular carcinoma by targeting 3′UTR of DNMT1." (PMID 27784307, 2016). "miR-140-5p also plays a tumor suppressor role in hepatocellular carcinoma by controlling NF-κB activity by directly regulating DNMT1 expression, and suppresses tumor growth and metastasis by targeting TGFBR1 and FGF9." (PMID 27588393, 2016). "The reduction in expression of SFRP1 and SFRP5 in hepatoma cells induced by HBx, correlates with the recruitment of DNA methyltransferase 1 (DNMT1) and DNMT3 to their promoters and subsequent hypermethylation." (PMID 27314335, 2016). "Previous studies have shown that inhibition or knockdown of DNA methyltransferase 1 (DNMT1) can restore MEG3 expression in human hepatocellular carcinoma cells and hepatic stellate cells." (PMID 27832204, 2016). "46, who showed that HDACi Trichostatin A down-regulates DNMT1 gene and protein expression and reduces global DNA methylation in the hepatoma cells." (PMID 25864732, 2015). "It was reported that miR-152 can target DNMT1 and induce aberrant DNA methylation in HBV-related hepatocellular carcinoma and that miR-152 targets DNMT1 in Nis-transformed cells via a feedback mechanism." (PMID 24987964, 2014). "In the current study, we investigated the effects of 5-aza-2'-deoxycytidine alone and suppression of DNMT1 or DNMT3B on human hepatoma cell lines." (PMID 27994704, 2008). "In this study, we try to knock down the expression of DNMT1 or DNMT3B via siRNA to explore the mechanism of DNMTs involved in hepatoma therapy." (PMID 27994704, 2008). "Another study confirmed the mechanism of inhibition of stemness in cancer cells (hepatocellular carcinoma) by casticin via DNMT1 suppression and evidenced for the first time the suppressive role that miRNA plays in the antitumor mechanism of casticin both in vitro and in vivo." (PMID 37304067, 2023). "Furthermore, we proved DNMT1 contributes the effect of ZNF191 on hepatoma cell growth via the PI3K‐AKT pathway." (PMID 35092191, 2022). "ARID2 mutations were enriched in clusters 1–2 with greater methylation changes, and a previous study in hepatocellular carcinoma indicates that ARID2 could recruit DNMT1 to the promoter, which increased promoter methylation." (PMID 35130881, 2022). "In the hepatocellular carcinoma Hepa 1-6 cell line, TSA could play a veritable role to prevent hepatocellular carcinoma leading to the inhibition of apoptosis and the reduction of DNMT1 expression." (PMID 34835969, 2021). "The aim of this study was to investigate the effect of zebularine on p16INK4a, p14ARF, p15INK4b, and DNA methyltransferase 1 gene expression, cell growth inhibition, and apoptosis induction in human hepatocellular carcinoma PLC/PRF5 and pancreatic cancer PA-TU-8902 cell lines." (PMID 33841535, 2020). "CircFoxp1 is a 587 bp circular RNA consisting of Foxp1 exons 8–11 and is involved in mesenchymal stem cell differentiation and hepatocellular carcinoma cell proliferation and metastasis, We here found that circFoxp1 recruited DNMT1 by binding to its host gene Foxp1 promoter." (PMID 32951006, 2020). "Moreover, in hepatocellular carcinoma, miR-29a modulates both the DNA methyl-transferase 1 (DNMT1) and DNMT3B." (PMID 29401683, 2018). "Similarly, in hepatocellular carcinomas, there is increased expression of DNMT1, DNMT3a, and DNMT3b and a progressive increase in the number of methylated genes from normal liver, chronic hepatitis/cirrhosis to hepatocellular carcinoma." (PMID 24822169, 2014). "Thus we identified that ZNF191/DNMT1/p‐AKT axis can promote hepatoma proliferation." (PMID 35092191, 2022).
hepatocellular carcinoma (continued). "ZNF191 is a novel transcription regulator for DNMT1, and the pro‐proliferation effect of ZNF191/DNMT1/p‐AKT axis in hepatoma cells implies that ZNF191 status in HCCs may affect the therapeutic effect of DNMTs inhibitors and PI3K inhibitors for precise treatment of the disease." (PMID 35092191, 2022). "Next we tested whether this ZNF191 activation of AKT pathway in hepatoma cells is DNMT1‐dependent." (PMID 35092191, 2022). "Epigenetic alteration of the p16INK4a, p14ARF, p15INK4b, and DNA methyltransferase 1 gene (DNMT1) expression occurs in hepatocellular carcinoma (HCC) and pancreatic cancer frequently." (PMID 33841535, 2020). "Previously, we evaluated the effect of 5-Aza-CdR on DNMT1 gene expression in hepatocellular carcinoma (HCC) which encouraged us to design the current study." (PMID 34466608, 2020). "In addition, overexpression of DNMT1, 3A, and 3B was correlated with tumorigenesis and other diseases, and DNMT3A expression was significantly associated with the prognosis of gastric and hepatocellular carcinomas in human." (PMID 29312436, 2017). "The downregulation of miR-152 induces abnormal DNA methylation in HBV-related hepatocellular carcinoma (HCC) by inhibiting DNA methyltransferase 1 (DNMT1) expression." (PMID 28056089, 2017). "In addition to these findings, the two intronic polymorphisms rs2241531 and rs4804490 of DNMT1 may be associated with hepatitis B virus (HBV) clearance and protection from the development of hepatocellular carcinoma." (PMID 23666104, 2013). "This pathway witnessed the increased expression of DNA methyltransferase 1 and EZH2, which resulted from HCC and hepatoma cells." (PMID 37626362, 2023). "In vascular endothelial cells, inhibition of mTOR by rapamycin decreases the expression of DNMT1, while in hepatocellular carcinoma cell lines Hep G2, SNU-182, and Hep 3B2.1-7, inhibition of mTOR with Torin-2 increases the expression of DNMT1." (PMID 36430934, 2022). "In hepatocellular carcinoma, TGF-β1 induces CD133 promoter demethylation by downregulating DNA methyltransferases 1 (DNMT1) and 3b (DNMT3b)." (PMID 35938167, 2022). "DNMT1 is a direct target of SGI, treatment of SGI depletes DNMT1 in hepatocellular carcinoma cell line." (PMID 30547810, 2018). "miR-152 has several targets, such as DNA (cytosine-5)-methyltransferase-1 (DNMT1) in endometrial cancer and TNFRF6B in hepatocellular carcinoma." (PMID 28895916, 2017). "In this article, we aimed to explore the potential protective effect of curcumin against UV radiation-induced DNMT1, DNMT3A, DNMT3B, HDAC5, and HDAC6 expression in immortalized keratinocytes (HaCaT), hepatocellular carcinoma (HepG2), and lung adenocarcinoma (A549) cells." (PMID 41901340, 2026). "In hepatocellular carcinoma, ARID2 represses EMT by recruiting DNMT1 to suppress SNAI138." (PMID 35945219, 2022). "Taken together, ZNF191 may function through upregulating DNMT1, regulating DNA methylation of genes involved in the PI3‐AKT pathway and activating the signaling to promote hepatoma cell proliferation." (PMID 35092191, 2022). "The sensitizing effect of acetylation modification on the responsiveness of hepatoma cells to anticancer therapy is ascribed to its modulatory role on epigenetics via the upregulation of HDAC1 and downregulation of Dnmt1 and 3α gene and drugs metabolizing genes." (PMID 36297347, 2022). "In Huh-7 human hepatocellular carcinoma (HCC) cells, Mybbp1a promotes the methylation of CpG islands within the IGFBP5 gene by binding to DNA methyltransferase 1 (DNMT1), thereby blocking IGFBP5 transcription." (PMID 36093095, 2022). "In liver cancer, DNMT1-mediated methylation of BEX1 promoter leads to different stemness of cells in hepatoblastoma (HB) and hepatocellular carcinoma (HCC) and a subtype of HCC with high CSC features (CSC-HCC)." (PMID 36010594, 2022).
hepatocellular carcinoma (continued). "Since DNMT1 is the foremost contributor in the mammalian DNA methylation machinery, and ZNF191 can transcriptionally regulate DNMT1 directly, we wondered whether ZNF191 can alter DNA methylation in hepatoma cells." (PMID 35092191, 2022). "Therefore, we examined the effect of ZNF191 on hepatoma cell growth with or without endogenous DNMT1 protein." (PMID 35092191, 2022). "BEX1, under the regulation of DNA methyltransferases 1 (DNMT1), was shown to have differential expression levels in Hepatoblastoma, CSC-hepatocellular carcinoma (HCC), and non-CSC HCC patients." (PMID 35659296, 2022).